CD151 (CD151 molecule (Raph blood group))
Description:
Structural component of specialized membrane microdomains known as tetraspanin-enriched microdomains (TERMs), which act as platforms for receptor clustering and signaling. Plays a role in various cellular and molecular mechanism through its association with both integrin and non-integrin proteins. These interactions facilitate critical cellular functions, including cell-to-cell communication, wound healing, platelet aggregation, trafficking, cell motility, and angiogenesis. Via interaction with JAM-A/F11R and integrin ITGA3:ITGB1, promotes the recruitment of signaling molecules such as RAC1, CDC42 and RhoGTPases to facilitate the polarization of epithelial cells and the reorganization of the actin cytoskeleton, which are critical steps in cell migration process. Regulates the glycosylation pattern of ITGA3:ITGB1 thereby modulating its activity. Plays an essential role in the maintenance of central laminin-binding integrin ITGA6:ITGB4-containing adhesion complexes. Essential for the proper assembly of the glomerular and tubular basement membranes in kidney. Contributes to T-cell activation by modulating integrin signaling leading to activation of downstream targets PTK2 and MAPK1/MAPK3. (Microbial infection) Plays a role in human papillomavirus 16/HPV-16 endocytosis upon binding to cell surface receptor. (Microbial infection) Plays a role in human cytomegalovirus entry into host cell by contributing to entry receptor binding, membrane fusion, or release of the capsid.
Synonyms: PETA-3; TSPAN24; SFA-1; RAPH; EBS7; GP27; MER2; SFA1
Tractability: Antibody: UniProt places it where antibodies can reach, with high confidence; its Gene Ontology location is reachable by antibodies, with high confidence; UniProt predicts a signal peptide or a membrane-spanning region. PROTAC: UniProt records ubiquitination sites on it; ubiquitination databases record sites on it; its protein half-life has been measured.
Gene: Protein-coding gene on chromosome 11 (832,705 to 839,831, forward strand). Ensembl gene ENSG00000177697.
Subcellular location: Cell membrane
Pathways (Reactome):
Cell-Cell communication: Type I hemidesmosome assembly
Extracellular matrix organization: Assembly of collagen fibrils and other multimeric structures
Gene Ontology:
Molecular function: integrin binding; protein binding
Biological process: positive regulation of cell migration; positive regulation of endocytosis; wound healing, spreading of cells; cell adhesion; cell migration
Cellular component: basement membrane; cell surface; focal adhesion; plasma membrane; cytosol; membrane
Genetic constraint (gnomAD): Loss-of-function variants: 20 observed, 35.6 expected, observed/expected ratio (o/e) 0.56, 90% interval 0.39 to 0.82. The upper end of that interval is the gene's LOEUF score, 0.82, which puts it in group 3 of 6, group 1 being the genes least tolerant of losing a copy. Missense variants: 306 observed, 337.45 expected, observed/expected ratio (o/e) 0.91, 90% interval 0.82 to 1. Synonymous variants: 157 observed, 136.94 expected, observed/expected ratio (o/e) 1.15, 90% interval 1.01 to 1.31.
Homologues: Orthologues: chimpanzee CD151 (100% identical), dog CD151 (94% identical), mouse Cd151 (94% identical), rat Cd151 (93% identical), macaque CD151 (92% identical), pig CD151 (89% identical), tropical clawed frog cd151 (77% identical), guinea pig CD151 (72% identical), zebrafish cd151l (72% identical), zebrafish cd151 (65% identical). Paralogues in human: TSPAN11 (56% identical), TSPAN4 (32% identical), TSPAN7 (30% identical), TSPAN9 (30% identical), TSPAN17 (29% identical), TSPAN6 (28% identical), CD9 (28% identical), TSPAN18 (28% identical), TSPAN8 (28% identical), CD37 (27% identical), CD82 (27% identical), TSPAN5 (27% identical), and 20 more.
Diseases named in the same sentence as CD151 in open-access papers:
CD151 is named in the same sentence as 126 diseases in open-access papers, as found by Europe PMC text mining. Sharing a sentence is not in itself a finding about the gene and the disease. The quoted sentences say what the papers report.
breast cancer (42 papers, 2010 to 2026). A primary or metastatic malignant neoplasm involving the breast. "For example, CD151, a Raph blood group antigen system gene which has been studied most frequently, was reported to be associated with poor prognosis in breast cancer and glioblastoma." (PMID 35955933, 2022). "This line of observation is consistent with the critical role of CD151-associated α6 integrin in human cancer stem cells across a wide range of human cancer types, particularly breast cancer and glioblastoma." (PMID 33919420, 2021). "In line with this evidence, CD151 expression appears elevated at the mRNA level in metastatic tumors and is associated with poor clinical outcomes in the ErbB2+ breast cancer subtype." (PMID 33919420, 2021). "CD9/CD81 also regulate α3β1 integrin, loss of these two tetraspanins impairs breast cancer spreading, motility, and disrupts its association with PKCα in a CD151-independent manner." (PMID 29946318, 2018). "The significant association was also detected between CD151 overexpression and poor OS in patients with breast cancer (OS: pooled HR = 1.399, 95% CI =1.022-1.915, P=0.036) and gastric cancer (OS: pooled HR = 1.498, 95% CI =1.188-1.890, P=0.001)." (PMID 27888619, 2017). "When data was stratified according to cancer type, associations between CD151 overexpression and poor OS were also significant in breast cancer and gastric cancer." (PMID 27888619, 2017). "High levels of the tetraspanin CD151 have been linked to poor patient outcome in several human cancers including breast cancer." (PMID 25012362, 2014). "In our study, CD151 overexpression was also associated with poor prognosis of breast cancer patients in line with its clinical significance in other types of cancer." (PMID 22294188, 2012). "CD151 expression has been reported to be associated with advanced cancer stage, cancer invasiveness and poor prognosis in endometrial cancer, hepatocellular carcinoma, breast cancer and non-small cell lung cancer patients." (PMID 36941633, 2023). "We propose that CD151 may be a potential therapeutic target for inhibiting cell proliferation, migration, and invasion of ERα+ breast cancer cells during partial EMT caused by ZEB1." (PMID 35440541, 2022). "Here we investigated the effect of Cd151 deletion on mammary tumorigenesis by crossing Cd151-deficient mice with a spontaneously metastasising transgenic model of breast cancer induced by the polyoma middle T antigen (PyMT) driven by the murine mammary tumor virus promoter (MMTV)." (PMID 25012362, 2014). "Whether the CD151-associated HER2-positive breast cancer represents an independent disease entity remains unanswered and needs to be clarified in future studies." (PMID 22294188, 2012). "However, the association of CD151 expression with clinical outcome as well as its significance as prognostic factor in breast cancer patients is still unclear." (PMID 22294188, 2012). "Because CD151 is associated with recurrence of basal-like breast cancer, it will be of interest to determine whether the CSC-associated role of CD151 is recapitulated by use of more clinically relevant PDX model of breast cancer under taxane-based regimens known to foster CSCs." (PMID 33919420, 2021). "Several studies in breast cancer, skin squamous cell carcinoma and glioblastoma have delved into the functional relationship between CD151 and EGFR18, 42, 43 in mediating cell spreading, invasion, colony formation or tumorigenesis." (PMID 38982031, 2024). "Through referring to others’ YB1-CLIP results (GSE63605), some onco-promoting gene mRNAs were found in the YB1-bound RNA library and the expression levels of HMGA1 and CD151 were investigated in breast cancer cells." (PMID 37035211, 2023). "CD151 ablation markedly reduces breast cancer cell migration, invasion by inhibiting FAK-Rac1 signaling and disrupting EGFR-α6 integrin collaboration." (PMID 36941633, 2023).
breast cancer (continued). "In a large cohort of breast cancer patients, elevated CD151 levels were significantly correlated with tumor stage, metastatic potential, and patient survival, and CD151 protein expression was higher in ERα– breast cancers." (PMID 35440541, 2022). "CD151 expression is considered a poor prognostic factor in solid tumors such as colon cancer, breast cancer, gastric cancer, and esophageal squamous cell carcinoma." (PMID 33767593, 2021). "As a result, our studies argue that CD151 is a suppressor of ER+ breast cancer and prostate cancer, as they frequently arise from oncogenic targeting of luminal or well-differentiated epithelial cells, rather than basal epithelial or progenitor cells." (PMID 33919420, 2021). "In line with this functional impact, the downregulation or deletion of CD151 in normal luminal progenitor cells or related breast cancer cell lines or mammary gland is accompanied by the upregulation of fibronectin expression and Slug." (PMID 33919420, 2021). "It was found that CD151 on serum or plasma-derived sEVs from breast cancer patients promoted breast cancer cell neovascularization and cancer cell metastasis." (PMID 34094979, 2021). "Another study showed that integrin α3β1 on sEVs secreted by breast cancer cells directly interacted with CD151 in tumor stromal cells, thereby mediating their metastasis to distant sites." (PMID 34094979, 2021). "More recently, we and others have detected a marked decrease in the formation of pulmonary metastases in breast cancer upon CD151 deletion or knockdown in MMTV-ErbB2 or MMTV-PyMT transgenic or xenograft model." (PMID 33919420, 2021). "Our recent study shows that upon CD151 deletion, there was more than 10-fold increase in the level of nuclear β-catenin as well as the strong cytosolic presence of E-cadherin in mammary tumors." (PMID 33919420, 2021). "Studies from our group and others indicate that the pro-metastatic role of CD151 in human basal-like and ErbB2 breast cancer subtypes is achieved largely through regulating α6 integrin-dependent cell motility, invasion and survival." (PMID 33919420, 2021). "Another developing theme on CD151 in breast cancer is its promoting role in development and growth of basal-like mammary tumors driven by the oncogenic Wnt1 pathway." (PMID 33919420, 2021). "The impact of CD151 was also reported in breast cancer in which mammary tumor initiation, tumor growth, survival, and metastasis were impaired in CD151-null mice." (PMID 32117989, 2020). "Another tetraspanin, namely CD151, was reported to exhibit membrane and cytoplasmic localisation in breast cancer." (PMID 30982971, 2019). "CD151 is correlated with poor prognosis in endometrial cancer, accelerates breast cancer cell invasion via integrin α6, and promotes prostate cancer migratory activity and lymphangiogenesis, increasing metastatic potential." (PMID 29867202, 2018). "MiR-124 suppresses tumour growth through targeting STAT3 in colorectal cancer, CD151 in breast cancer, and ERK in cutaneous squamous cell carcinoma." (PMID 29152130, 2017). "In breast cancer cell lines, authors showed that the expression of CD151, VIM, and SNAI2 were suppressed, while CDH1 (an epithelial marker) was upregulated by miR-506." (PMID 28405738, 2017). "In mammary cancer cells, the CD151-α3β1 integrin complex participates in invasive migration, which is blocked by PI3K inhibitor, suggesting the involvement of tetraspanin-integrin complex in cell invasion via PI3K-dependent pathway." (PMID 27270320, 2016). "Sadej and colleagues showed that CD151 is required for TGFβ1-induced proliferation and scattering of breast cancer cell line MDA-MB-231 through regulating TGFβ-induced p38 phosphorylation, rather than canonical TGFβ-induced Smad phosphorylation." (PMID 25978409, 2015). "In summary, the results of this study show that CD151 enhances mammary tumor initiation and progression in the MMTV/PyMT mouse model but no direct effect on metastasis was demonstrated." (PMID 25012362, 2014).
breast cancer (continued). "Firstly, similarly to our results in the PyMT breast cancer model, Takeda and colleagues have demonstrated that CD151 promotes tumor incidence and multiplicity in a skin carcinogenesis model." (PMID 25012362, 2014). "A recent study investigated the impact of Cd151 deletion on tumor onset, growth and metastasis of another well characterized mouse mammary tumor model, the MMTV/Neu model (overexpressing multiple copies of wild-type Neu, the rat homolog of ErbB2)." (PMID 25012362, 2014). "The findings from this study provide additional evidence that CD151 acts to enhance tumor formation initiated by a range of oncogenes and strongly support its relevance as a potential therapeutic target to delay breast cancer progression." (PMID 25012362, 2014). "In conclusion, our findings strongly support the relevance of CD151 as a potential therapeutic target to delay breast cancer progression." (PMID 25012362, 2014). "Here we show that Cd151–null mice develop smaller and fewer PyMT mammary tumors than their age matched controls." (PMID 25012362, 2014). "It is interesting to note that a study addressing the impact of Cd151 deletion in another mouse model of breast cancer (the ErbB2 model) has recently been published by Deng and colleagues." (PMID 25012362, 2014). "In this study, we observed that miR-506 played a role as a master suppressor of EMT in breast cancer through the direct targeting CD151, VIM and SNAI2." (PMID 23717581, 2013). "Our data reveal that the CD9/CD81 complex and CD151 have overlapping but distinct functions in regulating α3β1-dependent behaviors in the MDA-MB-231 breast cancer model." (PMID 23613949, 2013). "In the MMTV-ErbB2 mouse breast cancer model, phosphorylation of the β4 integrin cytoplasmic tail at the PKC-dependent S1424 site was reduced in the primary mammary tumors from CD151 knockout mice versus control mice." (PMID 23613949, 2013). "miR-506 suppressed the expression of mesenchymal genes such as Vimentin, Snai2, and CD151 in MDA-MB-231 human breast cancer cell line." (PMID 23717581, 2013). "Breast cancer patients with CD151 overexpression demonstrated a substantially lower OS with a 1.65-fold (P=0.034; HR, 1.65; 95% CI, 1.03–2.59) higher risk of death after adjusting for AJCC stage, breast subtype, and adjuvant chemotherapy." (PMID 22294188, 2012). "Intriguingly, in breast cancer models comparing CD151-expressing cells against CD151-ablated cells, tumor growth was delayed in the absense of CD151." (PMID 22272937, 2012). "The immunohistochemistry-based tissue microarray analysis showed that 127 (14.3%) cases overexpressed CD151 among 886 breast cancer patients." (PMID 22294188, 2012). "CD151 overexpression was detected more frequently in breast cancers with HER2 overexpression (21.9%) than in HER2-negative breast cancers (11.8%, P<0.001)." (PMID 22294188, 2012). "In the Cox regression model, the prognostic factors for OS in all of the patients were AJCC stage, breast cancer subtype, adjuvant chemotherapy, and CD151 overexpression." (PMID 22294188, 2012). "This protein is implicated in motility, invasion, and metastasis of cancer cells, but the prevalence of CD151 expression in subtypes of breast cancers and its influence on clinical outcome remains to be evaluated." (PMID 22294188, 2012). "Functionally, a CD151-targeting antibody was shown to inhibit cell migration in an in vivo breast cancer xenograft model and contain breast cancer cells within a single contiguous tumor." (PMID 22272937, 2012). "By contrast, variable patterns of CD151 expression were seen in the invasive breast cancer tissues, which ranged from absence to diffuse, strong overexpression occurred mainly in the membrane and/or cytoplasm of the tumour cells." (PMID 22294188, 2012). "In breast cancer, CD151 expression is increased in patients with invasive ductal carcinomas and this correlates with higher tumour grade and node metastasis." (PMID 21505452, 2011).
breast cancer (continued). "More recently, we have shown that CD151 can also regulate recruitment of breast cancer cells to the lungs and growth of the metastatic lesion." (PMID 21505452, 2011). "We selected tetraspanin CD151 as a marker based on studies in breast cancer, which demonstrated its prognostic utility in a subgroup of invasive ductal carcinomas." (PMID 21505452, 2011). "Similarly, in MDA-MB-231 breast cancer cells, the CD151 interaction with MET triggers AKT activation, leading to branching networks in matrigel." (PMID 39769452, 2024). "Moreover, CD151 has been shown to activate RhoA by facilitating integrin α3β1 and Rho controls dimerization of ErbB2, thus promoting motility and metastasis of breast cancer." (PMID 34108040, 2021). "Interestingly, in breast cancer cells exhibiting a strong promoting role of CD151, receptor tyrosine kinases (RTKs) (e.g., EGFR, ErbB2, c-Met and Ron) or K-Ras are frequently activated because of gene amplification/overexpression or mutations." (PMID 33919420, 2021). "In addition, it has been reported that CD151 is highly expressed in many solid tumors, such as breast cancer, gastric cancer and hepatocellular carcinoma." (PMID 34108040, 2021). "Furthermore, CD151 induces cancer metastasis by regulating transforming growth factor (TGF) β1 in breast cancer." (PMID 33767593, 2021). "In contrast to the role in ER− breast cancer (basal-like and ErbB2+) summarized above, CD151 appears to be tumor suppressive in some cases, for example, during the development and growth of ER+ mammary tumors in the mouse mammary tumor virus (MMTV) promoter-driven Wnt1 oncogene model." (PMID 33919420, 2021). "One of the noticeable observations from our study with the MMTV-Wnt model was the absence of tumor-initiating cells in CD151-deficient ER+ mammary tumors." (PMID 33919420, 2021). "Following this link, we speculate that CD151 might promote tumor growth in breast cancer largely through regulation of c-Myc-driven cellular metabolism." (PMID 33919420, 2021). "Furthermore, the subgroup analysis revealed that the associations between CD151 overexpression and the outcome endpoints (OS or TTP) were significant within the Asian region and European, as well in patients with breast cancer or gastric cancer." (PMID 27888619, 2017). "Notably in breast cancer, elevated expression of CD151 correlates with lymph node invasion and poor overall survival of patients with invasive ductal carcinoma." (PMID 25012362, 2014). "Altogether these data strongly indicate a role for CD151 in tumor growth and metastasis, suggesting that it could be used as a target molecule for the design of new breast cancer therapies." (PMID 25012362, 2014). "CD151 is part of the tetraspanin family and it forms tight complexes with β1 and β4 integrins, both of which have been shown to be required for tumorigenesis and/or metastasis in transgenic mouse models of breast cancer." (PMID 25012362, 2014). "In addition, the depletion of CD151 attenuates pulmonary metastasis of breast cancer cells by regulating TGFβ signaling." (PMID 23717581, 2013). "In addition, CD151-silenced MCF-10A breast cancer cells expressing ErbB2 also showed reduced β4 integrin phosphorylation at S1424 in response to EGF stimulation." (PMID 23613949, 2013). "CD151 was identified as a potential prognostic marker for breast cancer." (PMID 23586059, 2013). "Combination of these promoting effects of CD151 expression on breast cancer progression including tumour size and lymph node involvement may be responsible for a poor prognosis of breast cancer patients with high-CD151 expression." (PMID 22294188, 2012). "We also found that 16.2% of TNBC overexpressed CD151 and CD151-high cases showed a significantly poor OS consistent with the previous study demonstrating a role for CD151-α6 integrin complexes in basal-like breast cancer progression." (PMID 22294188, 2012).